RNU6-303P (RNA, U6 small nuclear 303, pseudogene)
Gene: Small nuclear RNA gene on chromosome Y (4,174,985 to 4,175,090, reverse strand). Ensembl gene ENSG00000252900.
Homologues: Orthologues: chimpanzee U6 (97% identical), macaque U6 (92% identical), guinea pig U6 (79% identical), mouse Gm22305 (78% identical), pig U6 (76% identical), dog U6 (72% identical). Paralogues in human: RNU6-555P (98% identical), RNU6-589P (87% identical), RNU6-1011P (86% identical), RNU6-1122P (85% identical), RNU6-166P (85% identical), RNU6-891P (85% identical), RNU6-1042P (84% identical), RNU6-116P (84% identical), RNU6-15P (84% identical), RNU6-259P (84% identical), RNU6-41P (84% identical), RNU6-44P (84% identical), and 1286 more.